ATP10A (ATPase phospholipid transporting 10A (putative))
Description:
Catalytic component of P4-ATPase flippase complex, which catalyzes the hydrolysis of ATP coupled to the transport of phosphatidylcholine (PC) from the outer to the inner leaflet of the plasma membrane. Initiates inward plasma membrane bending and recruitment of Bin/amphiphysin/Rvs (BAR) domain-containing proteins involved in membrane tubulation and cell trafficking. Facilitates ITGB1/beta1 integrin endocytosis, delaying cell adhesion and cell spreading on extracellular matrix. Has low flippase activity toward glucosylceramide (GlcCer).
Synonyms: ATP10C; ATPVA; ATPVC; KIAA0566
Tractability: Antibody: UniProt places it where antibodies can reach, with high confidence; its Gene Ontology location is reachable by antibodies, with high confidence; UniProt predicts a signal peptide or a membrane-spanning region.
Gene: Protein-coding gene on chromosome 15 (25,677,273 to 25,865,184, reverse strand). Ensembl gene ENSG00000206190.
Subcellular location: Cell membrane; Endoplasmic reticulum membrane
Pathways (Reactome):
Transport of small molecules: Ion transport by P-type ATPases
Gene Ontology:
Molecular function: ATPase-coupled intramembrane lipid transporter activity; glycosylceramide flippase activity; phosphatidylcholine flippase activity; phosphatidylcholine floppase activity; protein binding; ATP binding; ATP hydrolysis activity; magnesium ion binding; nucleotide binding
Biological process: positive regulation of membrane tubulation; monoatomic ion transmembrane transport; phospholipid translocation; regulation of cell shape; phospholipid transport
Cellular component: endoplasmic reticulum; endoplasmic reticulum membrane; phospholipid-translocating ATPase complex; plasma membrane; membrane
Genetic constraint (gnomAD): Loss-of-function variants: 108 observed, 144.53 expected, observed/expected ratio (o/e) 0.75, 90% interval 0.64 to 0.88. The upper end of that interval is the gene's LOEUF score, 0.88, which puts it in group 3 of 6, group 1 being the genes least tolerant of losing a copy. Missense variants: 1,870 observed, 1,929.7 expected, observed/expected ratio (o/e) 0.97, 90% interval 0.93 to 1.01. Synonymous variants: 837 observed, 821.31 expected, observed/expected ratio (o/e) 1.02, 90% interval 0.96 to 1.08.
Homologues: Orthologues: chimpanzee ATP10A (99% identical), macaque ATP10A (95% identical), dog ATP10A (85% identical), rabbit ATP10A (82% identical), rat Atp10a (81% identical), mouse Atp10a (81% identical), guinea pig ATP10A (81% identical), tropical clawed frog atp10a (63% identical), zebrafish atp10a (62% identical), Drosophila melanogaster CG31729 (20% identical), Caenorhabditis elegans tat-5 (19% identical), Caenorhabditis elegans tat-6 (19% identical). Paralogues in human: ATP10D (46% identical), ATP10B (46% identical), ATP8B2 (29% identical), ATP8B1 (28% identical), ATP8B4 (28% identical), ATP8A2 (28% identical), ATP8A1 (27% identical), ATP11B (26% identical), ATP8B3 (26% identical), ATP11C (25% identical), ATP11A (25% identical), ATP9A (20% identical), and 1 more.